ARRDC1 (arrestin domain containing 1)
Description:
Functions as an adapter recruiting ubiquitin-protein ligases to their specific substrates. Through an ubiquitination-dependent mechanism plays for instance a role in the incorporation of SLC11A2 into extracellular vesicles. More generally, plays a role in the extracellular transport of proteins between cells through the release in the extracellular space of microvesicles. By participating in the ITCH-mediated ubiquitination and subsequent degradation of NOTCH1, negatively regulates the NOTCH signaling pathway.
Synonyms: MGC40555
Tractability: Antibody: UniProt places it where antibodies can reach, with high confidence; its Gene Ontology location is reachable by antibodies, with high confidence. PROTAC: UniProt records ubiquitination sites on it; ubiquitination databases record sites on it; its protein half-life has been measured.
Gene: Protein-coding gene on chromosome 9 (137,605,619 to 137,616,227, forward strand). Ensembl gene ENSG00000197070.
Subcellular location: Cell membrane
Gene Ontology:
Molecular function: arrestin family protein binding; identical protein binding; protein binding; ubiquitin protein ligase binding; ubiquitin-like ligase-substrate adaptor activity
Biological process: extracellular transport; extracellular vesicle biogenesis; negative regulation of Notch signaling pathway; protein transport; protein ubiquitination; ubiquitin-dependent protein catabolic process
Cellular component: cytoplasmic vesicle; extracellular exosome; extracellular vesicle; plasma membrane; cytoplasm
Genetic constraint (gnomAD): Loss-of-function variants: 36 observed, 39.93 expected, observed/expected ratio (o/e) 0.9, 90% interval 0.69 to 1.19. The upper end of that interval is the gene's LOEUF score, 1.19, which puts it in group 5 of 6, group 1 being the genes least tolerant of losing a copy. Missense variants: 640 observed, 577.45 expected, observed/expected ratio (o/e) 1.11, 90% interval 1.04 to 1.18. Synonymous variants: 310 observed, 258.74 expected, observed/expected ratio (o/e) 1.2, 90% interval 1.09 to 1.32.
Homologues: Orthologues: chimpanzee ARRDC1 (99% identical), macaque ARRDC1 (96% identical), dog ARRDC1 (88% identical), pig ARRDC1 (87% identical), rat Arrdc1 (86% identical), mouse Arrdc1 (85% identical), rabbit ARRDC1 (81% identical), guinea pig ARRDC1 (66% identical), zebrafish arrdc1b (55% identical), tropical clawed frog arrdc1 (55% identical), Caenorhabditis elegans arrd-7 (23% identical), Caenorhabditis elegans arrd-18 (20% identical), and 9 more. Paralogues in human: ARRDC2 (24% identical), ARRDC4 (23% identical), ARRDC3 (21% identical), TXNIP (19% identical), ARRDC5 (15% identical).
Diseases named in the same sentence as ARRDC1 in open-access papers:
ARRDC1 is named in the same sentence as 15 diseases in open-access papers, as found by Europe PMC text mining. Sharing a sentence is not in itself a finding about the gene and the disease. The quoted sentences say what the papers report.
liver cancer (3 papers, 2021 to 2025). An epithelial or non-epithelial malignant neoplasm that arises from the liver. "Also, the abnormal expression or dysfunction of ARRDC1 is closely associated with the onset and progression of various diseases, including diabetes, colorectal cancer, and liver cancer." (PMID 41300841, 2025). "Therefore, ARRDC1 may function as an oncogene in liver cancer and promotes the metastasis of HCC." (PMID 35300565, 2022). "In liver cancer cells, SUMOylation of PKM2 induces plasma membrane targeting and exosomal excretion through interaction with ARRDC1." (PMID 34830854, 2021). "Moreover, ARRDC1 modulates the EMT of clear cell renal cell carcinoma via hippo pathways, whose activation, interestingly, inhibits liver cancer in vivo and in vitro." (PMID 35300565, 2022).
hepatocellular carcinoma (2 papers, 2022). A malignant tumor that arises from hepatocytes. "miR-124-3p binds to the 3′ UTR of arrestin domain containing 1 (ARRDC1), a protein involved in vesicular trafficking and EMT in hepatocellular carcinoma." (PMID 36497298, 2022).
asthma (1 paper, 2023). "Additionally, ARRDC1 (arrestin domain containing 1) is located in the extracellular vesicles (EVs), which are known to contribute to the pathogenesis of asthma via various mechanisms related to both inflammation and pathological remodeling." (PMID 37875944, 2023).
breast diseases (1 paper, 2025). "The results of GSEA revealed that ARRDC1 and ATP2A2 are co-enriched in multiple signaling pathways closely associated with the pathogenesis of breast diseases in both BBD and BC." (PMID 41300841, 2025). "In conclusion, this study implemented bioinformatics and ML algorithms to ascertain two key biomarkers (ARRDC1 and ATP2A2) for screening breast diseases, including BBD and BC." (PMID 41300841, 2025). "Therefore, ARRDC1 may serve as a reliable biomarker for breast diseases." (PMID 41300841, 2025). "In addition, the hormone signaling pathways jointly participated in by ARRDC1 and ATP2A2 are crucial in the development of breast diseases." (PMID 41300841, 2025).
glioma (1 paper, 2021). A benign or malignant brain and spinal cord tumor that arises from glial cells (astrocytes, oligodendrocytes, ependymal cells). "RPTOR amplification was found to be significantly associated with young adult BRCA (FDR = 0.020), while amplifications of KDM5A, CCND2, KRAS, and ARRDC1 were each suggestively associated with young adult gliomas (FDR ≤ 0.148)." (PMID 34788626, 2021).
viral infection (1 paper, 2025). "The process by which the Gag protein of human immunodeficiency virus type 1 (HIV-1) utilizes TSG101 to facilitate the release of virions is similar to that of ARMMs, suggesting a potential role for ARRDC1 in other virus infections." (PMID 40824091, 2025).
cancer (5 papers, 2020 to 2025). A tumor composed of atypical neoplastic, often pleomorphic cells that invade other tissues. "ARRDC2, ARRDC4, and TXNIP share common association with certain neurodegenerative diseases, while ARRDC1 is implicated in cancer." (PMID 38270169, 2024). "Studies have found that ARRDC1 plays a pivotal role in the malignant biological behaviors of cancer." (PMID 41300841, 2025). "However, the role of ARRDC1 in cancer, especially HCC, is not well understood." (PMID 35300565, 2022).
tumor (5 papers, 2022 to 2025). "PKM2’s SUMOylation promotes interaction with ARRDC1 and secretion via exosomes into the tumor microenvironment, activating STAT3 phosphorylation in monocytes and inducing their metabolic reprogramming and differentiation into macrophages." (PMID 40842995, 2025). "The ARRDC1 and ATP2A2 genes are primarily associated with macrophages, monocytes, follicular helper T cells, and NK cells, thereby reinforcing the link between immune infiltration and the tumor microenvironment." (PMID 41300841, 2025). "Non-canonical functions of PKM2 include its SUMOylation, which promotes interaction with ARRDC1 and secretion via exosomes into the tumor microenvironment, activating STAT3 phosphorylation in monocytes and inducing their metabolic reprogramming and differentiation into macrophages." (PMID 40842995, 2025). "Finally, we found that overexpression of ARRDC1 could rescue the anti-tumor effects of miR-124-3p." (PMID 35300565, 2022). "Moreover, macrophage-secreted cytokines/chemokines enhance ARRDC1-induced PKM2 ectosomal release from HCC cells, which form a feedback loop for carcinogenesis, monocyte-to-macrophage differentiation, and tumor microenvironment remodeling." (PMID 35300565, 2022).
infection (3 papers, 2016 to 2025). The state of being infected such as from the introduction of a foreign agent such as serum, vaccine, antigenic substance or organism. "The identification of ARRDC1 unveils alpha-arrestins as an important catalog of genes involved in fungal parasites during their infection process." (PMID 27498554, 2016). "Nonetheless, whether ARRDC1 plays a role in the infection of alphavirus remains unclear." (PMID 40824091, 2025). "At 24 h post-infection (p.i.), SINV RNA levels in ARRDC1-KO cells were increased by about 125-fold compared to the control cells." (PMID 40824091, 2025). "To investigate whether ARRDC1 affects other alphavirus replication, we infected the control cells and ARRDC1-KO cells with SINV (multiplicity of infection [MOI] = 1), another member of the Old World alphavirus." (PMID 40824091, 2025). "Arrdc1 is involved in a variety of processes including cellular protein metabolism, extracellular vesicle biogenesis, and negative regulation of the Notch signaling pathway.The down-regulated differential protein AIF1 has been identified as an up-regulated protein of infection." (PMID 36341346, 2022).
ARRDC1 also shares sentences with these, for which no sentence is quoted: colorectal cancer (2 papers); bladder cancer (1); clear cell renal cell carcinoma (1); diabetes (1); neurodegenerative disease (1); pancreatic cancer (1).